NHERF1 (NHERF family PDZ scaffold protein 1)
Diseases named in the same sentence as NHERF1 in open-access papers (continued):
Sharing a sentence is not in itself a finding about the gene and the disease.
cancer (continued). "Altogether, these data suggest that stimulation of cancer cells to develop invadopodia by plating on ECM occurs through the formation of a protein–protein complex formed by β1-integrin, ILK, p(T567)-ezrin, NHERF1 and NHE1." (PMID 33671549, 2021). "We studied a cohort of 115 CRC specimens including primary cancer (C) and adjacent normal mucosa (NM) by immunohistochemical double staining, analyzing the protein expression of MC-tryptase, PAR-2 and cytoplasmic NHERF1." (PMID 23991686, 2013). "Altogether, these data suggest that cancer cells develop functional invadopodia and perform subsequent invasion by establishing a compartmentalized, functional “signalsome” inside invadopodia, composed of β1-integrin, ILK, NHE1, p-ezrin and p-NHERF1." (PMID 33671549, 2021). "NHERF1-null mice do not have a direct cancer phenotype, but have lengthened intestines, indicating a growth regulatory function of NHERF1." (PMID 31002735, 2019). "Altogether, these data suggest that stimulation of cancer cells to develop invadopodia by plating on ECM, occurs through the formation of a protein-protein complex formed by NHE1, p-ezrin, ß1-integrin, PKA and p-NHERF1." (PMID 24086451, 2013). "According to the regulation efficacy data, the positive regulation of TRIM15 and NHERF1 by CREB1 was reversed from normal to cancer; the negative regulations of TCEAL2, RBPMS2 and FAM20C by CREB1 disappeared; and the negative regulation of FERMT2 was reversed from normal to cancer." (PMID 35421923, 2022). "It is no surprise for NHERF1 to alter the sensitivity or resistance to cancer drugs." (PMID 32164629, 2020). "It is now clear that NHERF1 promotes dimerization and activation of many tyrosine kinase receptors, such as the platelet derived growth factor receptor, the epidermal growth factor receptor and the HER2, known to directly regulate cell pathways related to cancer progression." (PMID 22439624, 2012). "Furthermore, the stimulation of cancer cells to develop invadopodia by plating on ECM, occurs through the formation of a a lipid raft compartmentalized functional protein-lipid-protein “signalsome” formed by NHE1, p-ezrin, PIP2, ß1-integrin and p-NHERF1 that promotes this activation of NHE1." (PMID 24086451, 2013).
infection (4 papers, 2016 to 2023). The state of being infected such as from the introduction of a foreign agent such as serum, vaccine, antigenic substance or organism. "This is the first report to determine the role of NHERF1 in fetal membrane inflammation and its potential contribution to infection-associated PTB and pPROM." (PMID 33092043, 2020). "Further, NHERF1 knockout models can demonstrate its functional contributions in infection associated PTB and its usefulness as an interventional target to reduce inflammation." (PMID 33092043, 2020). "This suggests that reducing NHERF1 is an ideal target for regulating infection/inflammation-associated preterm labor as it can downregulate NF-kB and increase IL-10." (PMID 33092043, 2020). "Downregulation of NHERF1 increased anti-inflammatory mediator IL-10, indicating that reducing NHERF1 expression could be a potential therapeutic strategy to reduce the risk of infection/inflammation associated with PTB." (PMID 33092043, 2020). "In conclusion, downregulation of NHERF1 increased anti-inflammatory IL-10, and reducing NHERF1 expression could be a potential therapeutic strategy to reduce the risk of infection/inflammation associated with PTB." (PMID 33092043, 2020). "More importantly, downregulation of NHERF1 increases anti-inflammatory IL-10, a cytokine that has been shown to inhibit preterm contractions in various animal models in response to infection and inflammation." (PMID 33092043, 2020). "Thus, our study suggests that infection-induced upregulation of NHERF1 increases NF-kB and subsequently increases overall inflammation." (PMID 33092043, 2020).
gynecological tumors (1 paper, 2022). "As the examples in this review highlight, NHERF1 exerts direct biological influences in gynecological tumors." (PMID 35223518, 2022). "In this review article, we describe the functional significance of NHERF1 in gynecological tumors." (PMID 35223518, 2022).
NHERF1 also shares sentences with these, for which no sentence is quoted: hepatocellular carcinoma (7 papers); Hypercalcemia (4); psoriasis (4); adenoma (3); gastric cancer (3); lymph node metastasis (3); osteoporosis (3); adenocarcinoma (2); autoimmune disease (2); CNS neoplasms (2); Dent disease (2); Nutritional rickets (2); Age-Related Hearing Loss (1); Alzheimer disease (1); anaplastic astrocytoma (1); Arthritis (1); autosomal dominant disease (1); benign prostatic hyperplasia (1); bladder cancer (1); blood cancer (1); breast adenocarcinoma (1); calcium-phosphorus metabolic disorder (1); Camurati-Engelmann disease (1); cervical squamous cell carcinoma (1); chondrosarcoma (1); chordoma (1); choroid plexus tumors (1); chronic kidney disease (1); colorectal adenoma (1); colorectal tumor (1).
A further 44 diseases each share a sentence with NHERF1 in 1 paper.